PLSCR1 (phospholipid scramblase 1)
Diseases named in the same sentence as PLSCR1 in open-access papers (continued):
Sharing a sentence is not in itself a finding about the gene and the disease.
COVID-19 (8 papers, 2020 to 2025). A disease caused by infection with severe acute respiratory syndrome coronavirus 2. "The H262Y mutation in PLSCR1 has been linked to increased susceptibility to severe COVID-19, as previously suggested by whole-genome sequencing data." (PMID 39945535, 2025). "Among the PLSCR1 variants identified in the COVID-19 GWAS cited above, only p.His262Tyr (rs343320) results in a protein-coding change, located in the NLS." (PMID 39316623, 2024). "A recent GWAS has identified an association between PLSCR1 variants and severe COVID-19 outcomes, reporting an odds ratio of approximately 1.2 and a p-value of approximately 10−8." (PMID 39316623, 2024). "Future human genetic studies are crucial for determining if certain PLSCR1 variants in the population cause increased risks of severe COVID-19." (PMID 39316623, 2024). "PLSCR1 variants have been linked to severe COVID-19 in a recent genome-wide association study (GWAS)." (PMID 39316623, 2024). "Several PLSCR1 variants were enriched in a GWAS on severe COVID-19, with a relatively low odds ratio of approximately 1.2." (PMID 39316623, 2024). "Additionally, genome-wide association study has predicted that PLSCR1 missense variants was associated with severe COVID-19, suggesting an important role PLSCR1 in antagonizing SARS-CoV-2 infection." (PMID 39945535, 2025). "Future research should aim to ascertain whether p.His262Tyr, or potentially other PLSCR1 variants, are directly responsible for elevated risks of severe COVID-19 in patients." (PMID 39316623, 2024). "Finally, we investigate the functional effects of PLSCR1 variants present in humans and discuss an association between PLSCR1 and severe COVID-19 reported recently." (PMID 39316623, 2024). "Phospholipid Scramblase 1 (PLSCR1, O15162) is associated with COVID-19." (PMID 39192889, 2024). "In other words, the GWAS suggests that PLSCR1 has a small but significant effect on severe COVID-19 risks." (PMID 39316623, 2024). "Our results corroborate a recent study from Xu and colleagues and provide an explanation for the enrichment for PLSCR1 SNPs observed in a GWAS on severe COVID-19." (PMID 39316623, 2024). "Our data collectively highlight PLSCR1’s function in restricting SARS-CoV-2 entry in cell culture, thereby clarifying the association between PLSCR1 variants and severe COVID-19 outcomes." (PMID 39316623, 2024). "Furthermore, we extend the recent characterization of PLSCR1 as an antiviral against SARS-CoV-2 impacting COVID-19 outcomes." (PMID 39316623, 2024). "This was attributed to a role of PLSCR1 in regulating the IFN response in COVID-19 patients." (PMID 39316623, 2024). "Subsequent cell–cell fusion assays found that the COVID-19-associated PLSCR1(H262Y) mutant did not inhibit membrane fusion despite retaining lipid scramblase activity." (PMID 37438530, 2023). "Notably, PLSCR1 was shown to impede the entry of multiple SARS-CoV-2 variants, including Alpha, Beta, Gamma, Delta, and Omicron, underscoring its potential as a broad-spectrum therapeutic target for COVID-19 and future coronavirus outbreaks." (PMID 39945535, 2025). "Thus, the COVID-19-associated H262Y mutation probably alters β-barrel surface or conformational properties rather than PLSCR1 nuclear translocation." (PMID 37438530, 2023).
acute myelogenous leukemia (7 papers, 2012 to 2022). "Plscr1 is required for normal myelopoiesis and reported to collaborate with Ca2+ to develop acute myeloid leukemia." (PMID 32555370, 2020). "Over expression of PLSCR1 is used as a prognostic marker for acute myelogenous leukemia (AML)." (PMID 35422844, 2022). "PLSCR1 expression level correlates with improved prognosis in acute myelogenous leukemia patients." (PMID 35422844, 2022). "For example, elevated expression of PLSCR1 is implicated in systemic lupus erythematosus and antiphospholipid syndrome, and increasing PLSCR1 mRNA expression is also suggested to increase the survival rate in acute promyelocytic leukemia and acute myelogenous leukemia patients." (PMID 32110987, 2020). "Multiple lines of evidence have demonstrated that increased expression of phospholipid scramblase 1 (PLSCR1) is involved in the differentiation of acute myeloid leukemia (AML) cells by several differentiation-inducing agents including ATRA and phorbol 12-myristate 13-acetate." (PMID 28492556, 2017). "PLSCR1 can suppress tumorogenesis by inducing cell differentiation in ovarian and leukemic cells and its expression has been proposed as a new positive prognostic marker for acute myelogenous leukemia." (PMID 23056603, 2012).
leukemia (7 papers, 2012 to 2023). A malignant (clonal) hematologic disorder, involving hematopoietic stem cells and characterized by the presence of primitive or atypical myeloid or lymphoid cells in the bone marrow and the blood. "RELL1 inhibits autophagy and also binds PLSCR1, and it is interesting to note that PLSCR1 also acts as an inhibitor of autophagy in both lymphoma and leukemia cells." (PMID 37893069, 2023). "Woogonoside, a natural flavonoid from Panax ginseng induces differentiation of U937 and HL-60 leukemia cells by upregulating PLSCR1." (PMID 35422844, 2022). "In U937 myeloid leukemia cells, PLSCR1 significantly decreases the proto-oncogene c-Myc and antiapoptotic Bcl-2 leading to suppression of leukemia." (PMID 35422844, 2022). "Wogonoside enhanced the expression of PLSCR1 and showed the highest anti-leukemia activity in samples (#2, #4 and #5) with low background PLSCR1 expression." (PMID 28492556, 2017). "PLSCR1, a regulator of cell proliferation, maturation, apoptosis and differentiation in leukemia." (PMID 31801484, 2019). "Our findings further clarify the key effect of nucleus PLSCR1 on leukemia differentiation therapy and suggest the mechanism of wogonoside’s anti-leukemic activity, supporting the potential of developing wogonoside as a novel therapeutic agent for clinical treatment of AML patients." (PMID 28492556, 2017).
ovarian carcinoma (7 papers, 2012 to 2025). A malignant neoplasm originating from the surface ovarian epithelium. "PLSCR1 expression was also implicated in ovarian cancer response to arsenic trioxide, a pro-apoptotic and pro-autophagic agent." (PMID 27248824, 2016). "Further studies are needed to explore the underlying mechanism of PLSCR1’s regulation on ISG expression in fibroblasts and ovarian carcinoma cells." (PMID 40248364, 2025). "The cancer genome atlas (TCGA) analysis revels that PLSCR1 is oncogenic and highly over expressed in ovarian carcinoma." (PMID 35422844, 2022). "PLSCR1 exhibits anti-proliferative and anti-tumor activity on human ovarian epithelial cancer cells." (PMID 35422844, 2022). "To address this question, we reduced SnoN expression via siRNA in HEY ovarian carcinoma cells (cell line used previously to investigate role of SnoN and PLSCR1); this was followed by quantitation of PLSCR1 mRNA levels via real-time PCR." (PMID 23621864, 2013). "The role of PLSCR1 in ovarian cancer and in modulating response to chemotherapeutic agents has yet to be fully understood." (PMID 23621864, 2013). "Similar to SnoN, PLSCR1 expression was low in normal immortalized T80 ovarian cells and highly expressed in the ovarian cancer cell lines." (PMID 23621864, 2013). "Our findings warrant further investigation into the role of PLSCR1 in ovarian cancer development and chemoresistance." (PMID 23621864, 2013). "Indeed, a pioneering study showed that PLSCR1 potentiates the transcriptional response to IFN-β treatment in human ovarian carcinoma Hey1B cells." (PMID 39316623, 2024). "Interferon (IFN-2α) and anti-cancer drug As2O3 modulate level of PLSCR1 in ovarian carcinoma cells." (PMID 35422844, 2022). "The role of PLSCR1 in inflammation or innate immunity in ovarian cancer development is currently unknown and needs to be further investigated." (PMID 25658875, 2015). "However, similar to our previous results in the HEY ovarian cancer cell line, we observed that PLSCR1 protein was markedly induced from 6 until 24 hours (basal PLSCR1 protein level is very low)." (PMID 25658875, 2015). "Both IFN-2α and As2O3 treatment can modulate PLSCR1 mRNA levels in ovarian carcinoma cells." (PMID 23621864, 2013). "Collectively, these results demonstrate that, PLSCR1 is increased at the DNA and RNA levels in ovarian cancers and cell lines in comparison to normal cells, similar to SnoN, and can be co-amplified in a certain proportion of ovarian cancer specimens." (PMID 23621864, 2013). "In order to determine whether PLSCR1 plays a role in modulating As2O3–induced cell death response in ovarian cancer cells, we reduced PLSCR1 expression via siRNA." (PMID 23621864, 2013). "In ovarian cancers with PLSCR1 amplification, SnoN is gained." (PMID 23621864, 2013). "Furthermore, the DNA copy number of PLSCR1 and SnoN is nearly always the same in ovarian cancer cell lines (R2 = 0.6411)." (PMID 23621864, 2013). "However, PLSCR1 regulates SnoN/SkiL-dependent pathway in ovarian cancer cells." (PMID 35422844, 2022). "However, since HepG2 cells are a hepatocellular carcinoma cell line, it is possible that the mechanism leading to viral-mediated reduction in PLSCR1 expression may be similar to what we observed in our ovarian carcinoma cell lines treated with dsDNA." (PMID 25658875, 2015). "We first assessed whether PLSCR1 protein is altered upon As2O3 treatment in ovarian cancer cells." (PMID 23621864, 2013). "Following 48 hours post-dsDNA transfection, we noted that, in contrast to T80 cells, the ovarian cancer cell lines did not elicit an increase in PLSCR1 protein but rather there was a subtle reduction in its expression." (PMID 25658875, 2015). "We noted that PLSCR1 induction was observed only in normal but not in ovarian carcinoma cells." (PMID 25658875, 2015).
ovarian carcinoma (continued). "In contrast to normal T80/HMECs, the phosphorylation of IRF3 as well as induction of STING and PLSCR1 were absent in ovarian cancer cells (serous, clear cell, and endometrioid) suggesting that the STING/IRF3 pathway may be dysregulated in these cancer cells." (PMID 25658875, 2015). "In contrast to T80 and HMEC cells, we did not observe increases in PLSCR1 expression (or p-IRF3) in ovarian cancer cell lines, despite similar transfection efficiencies between T80 and the ovarian cancer cell lines (HEY, TOV21G, and TOV112D)." (PMID 25658875, 2015).
colorectal cancer (5 papers, 2012 to 2023). A primary or metastatic malignant neoplasm that affects the colon or rectum. "Both PLSCR1 and 3 are secreted through MVs of colorectal cancer cells that contain signaling machinery for colorectal tumorogenesis." (PMID 35422844, 2022). "Nevertheless, a number of reports have highlighted the possible beneficial effects of PLSCR1 targeting in colorectal cancers, hepatic cancers, and lung adenocarcinoma, where blockade or silencing of this protein resulted in the inhibition of tumor growth and metastasis." (PMID 35650588, 2022). "PLSCR1 is over expressed in human colorectal cancer (CRC) cells and hepatic cancer cells." (PMID 35422844, 2022). "PLSCR1 interacts with Fas-ligand that is related to the hepatic metastasis of colorectal carcinoma." (PMID 35422844, 2022). "Previously, we showed that PLSCR1 is overexpressed in many colorectal carcinomas (CRCs)." (PMID 23259795, 2012).
systemic lupus erythematosus (5 papers, 2020 to 2025). An autoimmune multi-organ disease typically associated with vasculopathy and autoantibody production. "Additionally, expression of PLSCR1 has been shown to be increased in monocytes of a subset of humans with systemic lupus erythematosus (SLE) at elevated risk for blood clotting, and in the monocytes of humans with anti-phospholipid syndrome." (PMID 33091028, 2020). "Notably, the expression level of PLSCR1 was upregulated in several chronic autoimmune diseases, including systemic lupus erythematosus (SLE), suggesting the potential involvement in the regulation of inflammatory responses." (PMID 41146421, 2025). "PLSCR1 expression was significantly upregulated in whole blood samples and peripheral blood mononuclear cells from patients with systemic lupus erythematosus (SLE), a chronic autoimmune disease with multiple organ involvement, in which autoantibodies and immune complexes induce tissue damage." (PMID 35650588, 2022).
hepatic carcinoma (4 papers, 2015 to 2025). "More importantly, the same study documented that patients with low plasma levels of PLSCR1 were at higher risk to develop hepatocellular carcinoma." (PMID 35650588, 2022). "PLSCR1 induced proliferation and migration of hepatic carcinoma cells through the interaction with the multifunctional growth factor midkine (MK) within the nucleus." (PMID 35650588, 2022). "We conducted a luciferase assay to evaluate the regulation of PLSCR1 gene expression by rs1061307 using the Jurkat cells (human T lymphocytes) and HepG2 cells (human liver carcinoma cells)." (PMID 35769989, 2022).
Allergy (3 papers, 2017 to 2022). An allergy is an immune response or reaction to substances that are usually not harmful. "The modulatory ability of PLSCR1, allowing increased as well as decreased biological responses, might serve to sophisticatedly regulate inflammation, host defense, tissue remodeling and homoeostasis and provide a rationale for exploiting PLSCR1 as therapeutic target in allergies." (PMID 31191542, 2019).
influenza (3 papers, 2018 to 2025). An acute viral infection of the respiratory tract, occurring in isolated cases, in epidemics, or in pandemics; it is caused by serologically different strains of viruses (influenzaviruses) designated A, B, and C, has a 3-day incubation period, and usually lasts for 3 to 10 days. "Phospholipid scramblase 1 (PLSCR1) is an interferon-stimulated gene (ISG) that has several known anti-influenza functions." (PMID 41439508, 2025). "The goals of this project are to determine the roles of Plscr1 in an IAV-infected mouse model, to implicate its involvement in IFN-λ signaling, and to elucidate the cell types responsible for Plscr1-mediated anti-influenza activities." (PMID 41439508, 2025). "To uncover any anti-influenza functions of Plscr1 in mice, we employed WT and Plscr1-/- mice and exposed them to IAV infection." (PMID 41439508, 2025). "While the only previously published Plscr1-/- mouse flu model focused on an H1N1 SIV infection, our data showed both similarities and discrepancies." (PMID 41439508, 2025). "The potential of PLSCR1 agonists that target ciliated airway epithelial cells as therapeutic treatments for influenza holds promise for future medical interventions." (PMID 41439508, 2025). "Our research will elucidate virus-host interactions and pave the way for the development of novel anti-influenza drugs that target human elements like PLSCR1, thereby mitigating the emergence of drug-resistant IAV strains." (PMID 41439508, 2025). "Using an enzymatically inactive mutant of PLSCR1, we uncoupled its lipid scramblase activity from anti-influenza activity." (PMID 41439508, 2025). "The absence of further disease exacerbation or increased viral titers in Plscr1-/-;Ifnlr1-/- mice compared to Ifnlr1-/- mice indicates that the anti-influenza activity of Plscr1 is largely dependent on Ifn-λr1." (PMID 41439508, 2025). "We found that the stable overexpression of PLSCR1 suppressed the nuclear import of NP, hindered the virus life cycle, and significantly inhibited the replication of various influenza subtypes." (PMID 29352288, 2018). "Therefore, ciliated epithelial cell-specific overexpression of Plscr1 is sufficient to provide anti-influenza protection through IFN-λ signaling." (PMID 41439508, 2025). "Therefore, as one of the earliest induced ISGs, Plscr1 constitutes the frontline defense against influenza infection." (PMID 41439508, 2025). "Previous studies have described some critical anti-influenza activities of PLSCR1." (PMID 41439508, 2025). "were the first to demonstrate the anti-influenza effects of PLSCR1 in a mouse model." (PMID 40248364, 2025). "We are the first group to demonstrate the roles of Plscr1 in a mouse-adapted human IAV-infected mouse model, to implicate its IFN-λ signaling-related mechanisms, and to elucidate the cell types that are responsible for Plscr1-mediated anti-influenza activities." (PMID 41439508, 2025). "Furthermore, we found that the enzymatic activity of PLSCR1 is dispensable for its anti-influenza function." (PMID 41439508, 2025). "Finally, ciliated airway epithelial cells are the primary cell type in the lung for mounting PLSCR1-mediated anti-influenza responses." (PMID 41439508, 2025). "Therefore, ILDR1 inhibitors may enhance PLSCR1’s anti-influenza activities." (PMID 40248364, 2025). "Requirement of both nuclear and surface PLSCR1 but not the enzymatic activity in IFN-λR1-mediated anti-influenza activities." (PMID 41439508, 2025).
lymphoma (3 papers, 2016 to 2023). A malignant (clonal) proliferation of B- lymphocytes or T- lymphocytes which involves the lymph nodes, bone marrow and/or extranodal sites. "Immunoblotting experiments carried out with 6 MCL primary cultures (MCL4, MCL5, MCL6, MCL7, MCL8, and MCL10) confirmed the heterogeneity of PLSCR1 basal levels in this lymphoma, and showed a marked induction of PLSCR1 expression by RA/IFN-α combination in all samples." (PMID 27248824, 2016). "In addition, PLSCR1 expression was detected by immunohistochemistry in lymphoma cells of a fraction of MCL biopsies, although with a broad heterogeneity both inter- and intra-patient." (PMID 27248824, 2016). "More importantly, analysis of a pilot series of MCL samples disclosed that PLSCR1 is heterogeneously expressed by these lymphomas, suggesting a possible influential relevance of this protein especially as putative predictive marker of clinical response to autophagy-inducer therapeutic agents." (PMID 27248824, 2016). "In summary, PLSCR1 is heterogeneously expressed by these lymphomas and chemotherapeutic regimes currently used in MCL management, including anthracyclines, could induce PLSCR1 expression suggesting a potential role of this protein in mediating tumor response to anticancer therapies." (PMID 27248824, 2016).
Sepsis (3 papers, 2022 to 2025). Sepsis is defined as life-threatening organ dysfunction caused by a dysregulated host response to infection. "Upregulation of TNFAIP6 and PLSCR1 was validated using public monocyte datasets and real-time PCR of mouse PBMCs, with PLSCR1 showing markedly increased expression in SLE cases complicated by sepsis." (PMID 41462079, 2025).
breast tumors (2 papers, 2015 to 2020). "We then assessed the association of PLSCR1 expression with histological grades of breast tumors in GSE25066, NKI295, GSE7390, GSE22358, and MEBTABRIC datasets in which tumors had the malignancy grading scores." (PMID 32292520, 2020). "We analyzed a proteogenomic dataset containing 36 breast tumor samples 27, and found PLSCR1 protein expression to be significantly higher in BLBC than in other subtypes." (PMID 32292520, 2020). "To confirm this observation, we analyzed PLSCR1 levels in both the nucleus and cytoplasm of breast tumor tissues." (PMID 32292520, 2020).